MYC (MYC proto-oncogene, bHLH transcription factor)
Diseases named in the same sentence as MYC in open-access papers (continued):
Sharing a sentence is not in itself a finding about the gene and the disease.
prostate carcinoma (continued). "Notably, NANOG was demonstrated to reprogramme prostate cancer cells by repressing the AR signalling axis and activating its own distinct transcriptional programme as well as engaging that of others such as MYC, leading to acquisition of a castration-resistant stem cell-like state." (PMID 30742096, 2019). "Moreover, rs378854 can also interact with MYC or PVT1 promoter in prostate cancer." (PMID 31309249, 2019). "Our findings demonstrate that MYC suppression is an important pharmacodynamic marker of BET bromodomain inhibitor response and suggest that targeting MYC may be a promising therapeutic strategy to overcome de novo BET bromodomain inhibitor resistance in prostate cancer." (PMID 30846826, 2019). "That so many of the genes encoding well-known Myc-interacting proteins are found in this analysis could be due to the fact that MYC is such an active and important driver of prostate cancer that the whole genome is reorganized to make its downstream targets more accessible." (PMID 28592290, 2017). "Moreover, addition of MYC/MAX to PrKD1 centered biomarker panel may improve the performance of the panel in discriminating indolent from aggressive prostate cancer." (PMID 29108267, 2017). "The SNPs identified are mainly in regions that had not previously been known to be associated with prostate cancer risk that might be clinically relevant, such as MYC, MSMB, KLK2 and KLK3 genes." (PMID 27819754, 2017). "Moreover, prostate cancer cells with higher SIRT3 protein level expressed lower c-MYC level." (PMID 26317998, 2015). "The oncogene c-MYC located at 8q24 encodes a transcription factor involved in cell cycle progression, cell growth, proliferation, protein synthesis, mitochondrial function, stem cell renewal, and DNA replication. c-MYC is amplified in approximately 70% of clinical prostate cancer." (PMID 25243131, 2014). "However, targeting MYC expression still represents an intervention option in prostate cancer, as demonstrated by the antisense-nucleotide approach in models of prostate cancer, where targeting MYC results in the suppression of proliferation and the reduction of prostasphere formation." (PMID 24293458, 2013). "In addition, FOXP3 was reported as to be a repressor of the oncogene c-MYC in prostate cancer." (PMID 23888189, 2012). "In this context, our demonstration that MYC overexpression can convert AKT-activated mouse prostate tumors from rapalog-sensitive to rapalog-resistant has implications for clinical studies of PI3K-pathway inhibitors in men whose prostate cancers also harbor increased AKT signaling." (PMID 21394210, 2011). "In light of the relatively disappointing single agent activity of rapalogs in prostate cancer, it may be critical to assess the MYC status of prostate tumors (among several other markers) to guide the interpretation of response data in patients undergoing PI3K inhibitor therapy." (PMID 21394210, 2011). "It is possible, therefore, that Nkx3.1 expression in invasive prostatic acini in MYC-driven mouse prostate cancers may represent a recapitulation or caricature of the process of stromal invasion/branching morphogenesis in development, and, that Nkx3.1 may facilitate this process." (PMID 20195545, 2010). "A recent result may shed light on why MYC is overexpressed in at least some prostate cancers." (PMID 20195545, 2010). "In addition, c-MYC overexpression in prostate cancer cells enables androgen-independent growth." (PMID 18190704, 2008). "However, the precise role of MYC in prostate cancer progression needs further clarification." (PMID 17146477, 2007). "The majority of analyzed prostate cancer cell lines were dependent on endogenous CMV for cell survival, reminiscent of addiction to oncogenes such as MYC, a protein that, similar to latent viruses, promotes immune evasion." (PMID 40493023, 2025).
prostate carcinoma (continued). "Specifically, in prostate cancer, PI3K activation and MYC-induced lipid metabolism promote glycolysis and contribute to metabolic heterogeneity." (PMID 41179661, 2025). "In mouse prostate cancer xenografts, POM121 drives tumor progression through importin-β-dependent nuclear import of androgen receptor, E2F1 and MYC, whereas importin-β inhibitor importazol attenuated tumor growth." (PMID 38177114, 2024). "We found that the 3′UTRMYC1-18 degraded c-MYC in two medulloblastoma lines (DAOY and D283med) and prostate cancer (C4-2B) and impaired their viability." (PMID 39123391, 2024). "We next examined three key prostate cancer oncogenes known to have regional enhancer interactions: FOXA1, MYC and AR4,5,45–49." (PMID 39020220, 2024). "By inferring the Decipher prognostic gene signature in the prostate cancer dataset (GSE116918), differences in fibroblast cells, androgen receptor (AR), and MYC proto-oncogene (MYC) TF activity between the two patient subgroups are observed." (PMID 39574035, 2024). "Findings from the MYC-inducible human Burkitt lymphoma model P493 and PC3 human prostate cancer cells affirm that MYC primarily suppresses POX/PRODH expression by up-regulating miR-23b." (PMID 38544804, 2024). "As such, POM121 promoted lethal prostate cancer through binding to importin-β, leading to nuclear import of oncogenic transcription factors (E2F1, MYC e.a.)." (PMID 38177114, 2024). "Bioinformatics analysis showed that MYC gene was highly expressed and CCND1 and MAPK1 were low expressed in prostate cancer tissues." (PMID 39061044, 2024). "ATF4 and c-MYC promote tumor cell growth by synergistically regulating MTHFD2, and MTHFD2 is identified as a biomarker or therapeutic target for prostate cancer." (PMID 38336749, 2024). "However, when treated with Guttiferone K, the c-MYC protein was degraded by the stabilization of FBXW7, and cell cycle re-entry was hindered in prostate cancer cells, suggesting that manipulating the protein levels of MYC could further regulate the quiescent-to-proliferative switch." (PMID 36835173, 2023). "In prostate cancer, BRD4 and MYC are direct substrates of SPOP, and the stabilization of BRD4 is directly linked to BETi resistance in prostate cancer cells carrying SPOP mutations." (PMID 37036970, 2023). "In prostate cancer, CCAT2-driven MYC activation can specifically increase the expression of beta-galactosidase, a key enzyme in energy production that provides monosaccharides for glycolysis." (PMID 37443779, 2023). "Our study thus far reveals that both pharmacological and genetic perturbation of MYC activity leads to upregulation of the metabolic enzyme GFAT1 and enhanced glycosylation in prostate cancer models." (PMID 36632215, 2023). "In prostate cancer, lncRNA RP11-1023L17.1 acts as an oncogene, regulating MYC’s transcriptional signature, and its depletion leads to the downregulation of MYC-dependent oncogenic features in a tumor." (PMID 37755396, 2023). "The molecular mechanisms driving prostate cancer have been intensively investigated, and involve hormone-driven signalling pathways, “classical” oncogenes including ERG and MYC, and tumour suppressors like PTEN." (PMID 37752235, 2023). "Among Chr8q24 gene located approximately 725 kb upstream of the MYC oncogene, PCAT1 was initially found in prostate cancer and is involved in the occurrence and development of prostate cancer." (PMID 35692795, 2022). "Consistent with studies demonstrating upregulation of c-MYC and N-MYC as well as TOPK in prostate cancer, these molecules were expressed at high levels." (PMID 36970725, 2022). "Here, we show that growth inhibition of prostate cancer models by SPA required high androgen receptor (AR) activity and were driven in part by downregulation of MYC." (PMID 36194476, 2022).
prostate carcinoma (continued). "Our bioinformatics analysis from TCGA dataset showed, for prostate cancer tissues, a positive correlation of mRNA expression of MYH9 with mRNA expression of GSK3β, β-catenin, cyclin D1, c-MYC, vimentin, and N-cadherin." (PMID 35589707, 2022). "The expressions of AR, MYC and FOXA1 genes themselves are frequently amplified in advanced prostate cancer by copy amplification and/or enhancer duplication." (PMID 34937944, 2022). "Conversely, a small molecule inhibitor targeting IRE1α was shown to decrease c-MYC levels and inhibit growth of prostate cancer cells and tumors, demonstrating a regulatory feedback loop between XBP1 and c-MYC." (PMID 35349489, 2022). "MYC mRNA was highly expressed in the INTS14 mRNA high-expression group in prostate and liver cancer cell lines in the database, PC-3 cells (prostate cancer-derived cells) and HuH-7 cells (liver cancer-derived cells) were utilized for the following experiments." (PMID 35887071, 2022). "Altogether, our study revealed an intricate crosstalk between the AR, MYC, FOXA1 and RNA Pol II resulting in a corrupted AR transcriptional program and promoting prostate cancer initiation and progression to the mCRPC stage." (PMID 35562350, 2022). "We report that high AR activity is required for growth inhibition of prostate cancer models by SPA, which occurs, in part, through downregulation of MYC." (PMID 36194476, 2022). "In support, elevated MYC expression was detected in both ICC/IDC and Gleason pattern 3 prostate cancer by IHC." (PMID 36229464, 2022). "In prostate cancer, USP22 predicts disease outcome and promotes the CRPC phenotype by controlling AR and MYC dual regulation." (PMID 35935969, 2022). "For this purpose, a recently conducted experiment has shown that overexpression of ARGs such as FAM215A, MYC and FADD can provide a poor prognosis and low overall survival rate of prostate cancer patients." (PMID 35317831, 2022). "A-485 and I-CBP112 co-operatively reduce CBP/p300 occupancy at chromatin and the expression of androgen-dependent oncogenes such as MYC and PSA, and synergistically suppress prostate cancer cell proliferation." (PMID 35836809, 2022). "In many cases, such as for AR, MYC, and FOXA1, these hotspots overlap with active chromatin marks and likely represent distal regulatory regions for neighboring prostate cancer genes, as shown by our analyses overlapping SVs with ChIP-Seq on mCRPC specimens." (PMID 35943799, 2022). "Our results indicate that high prostate cancer AR activity is required for tumor regression by BAT, which occurs in part through downregulation of MYC." (PMID 36194476, 2022). "MYC expression reduces SAM and increases SAH levels in prostate cancer, and these effects are exacerbated by high-fat diet." (PMID 34109280, 2021). "We observed a similar effect of I-CBP112, which targets the CBP/EP300 bromodomain, on the mitotic division in a culture of MDA-MB-231, whereas a substantial reduction in c-MYC, which is considered a TNBC driver, was observed in prostate cancer." (PMID 34572840, 2021). "Both ADAMTS and MMP family members are known to be BMI1 targets in GIC and NPC, as assessed by ChIP Seq, and their predicted upstream regulator, MYC, has also been described to be controlled by BMI1 in prostate cancer." (PMID 34316702, 2021). "The top 30 protein targets with high frequency were CCND1, EGFR, ESR1, and MYC, which can be used as the potential targets of XHP in the treatment of prostate cancer." (PMID 35342388, 2021).
prostate carcinoma (continued). "Consistent with our findings, c-MYC was activated, whereas c-SRC was inhibited via downregulated miR-206/613 in prostate cancer cell." (PMID 34857003, 2021). "Some studies have suggested that MYC cooperates with the dysregulation of the PI3K/AKT/mTOR pathway to promote PCa cell survival and promote oncogenic signaling in prostate cancer." (PMID 39697534, 2021). "c-MYC, also significantly downregulated with CYP3A5 siRNA treatment, is one of the key genes amplified in prostate cancer progression." (PMID 32316460, 2020). "In prostate cancer, FOXM1 is required for the pathogenesis of prostate tumors, and its expression is regulated by MYC." (PMID 32629770, 2020). "Then, we evaluated the gene expression profiles for the six HUB nodes (ABL1, EP300, FYN, MYC, PSMB2, and SRPK2) in all the prostate cancer cells, compared to normal prostate EPN cells." (PMID 32933107, 2020). "Knockdown of MYC expression in prostate cancer cells increased the expression of MEIS1 and increased the occupancy of MYC at the MEIS1 locus." (PMID 32681068, 2020). "For example, HOXC6 and DLX1 genes, which are biomarkers and key players of prostate cancer development as well as genes involved cell cycle (CDK4, CDC23, MYC) and androgen signaling (AR, GRHL2) are found." (PMID 31515496, 2019). "Our findings suggest that in primary prostate cancer, dietary SFI contributes to tumour progression by mimicking MYC over expression, setting the stage for therapeutic approaches involving changes to the diet." (PMID 31554818, 2019). "CNAs at the level of MYC, MYCN, GSK3B, MTOR, and BRCA2 are more frequently detected in germline BRCA2-mutant prostate cancers than in sporadic localized cancers." (PMID 31366128, 2019). "MYC is a well-described BRD4 target gene in multiple cancer types, and prior work demonstrates that MYC plays an important role in promoting prostate cancer cell survival." (PMID 30846826, 2019). "Transcriptome analyses demonstrated that the expression levels of various cancer-drivers/oncogenes, including MYC and MYB, were negatively correlated with that of TSPX in both LNCaP cells and clinical prostate cancer samples." (PMID 30863497, 2019). "MYC, ATF3, PMEPA1, AURKB, and HMOX-1 were identified as novel targets of curcumin in both less aggressive and highly aggressive metastatic prostate cancer cells in our study." (PMID 31581661, 2019). "Silencing of CTBP2 markedly increases apoptosis of prostate cancer cells; decreases the expression of IL-8, AT2R, CCND1, MMP9, MYC, and HSPC111; and reduces tumor growth in mouse xenograft model of human prostate cancer." (PMID 31323811, 2019). "MYC is frequently upregulated in 70–90% of both prostatic intraepithelial neoplasia (PIN) and prostate cancer lesions, and the high-level MYC expression contributes to the initiation and progression of prostate cancer." (PMID 30863497, 2019).
prostate carcinoma (continued). "Here we show that a patient-derived prostate-specific microbe, CP1, in combination with anti-PD-1 immunotherapy, increases survival and decreases tumor burden in orthotopic MYC- and PTEN-mutant prostate cancer models." (PMID 29686284, 2018). "In prostate cancer, prostate cancer gene expression marker 1 (PCGEM1) is a long coding RNA that can interact with MYC directly and enhance its activity." (PMID 28362357, 2017). "KEGG pathway enrichment analysis revealed that the significantly enriched pathways were PI3K-Akt signaling, prostate cancer, cell cycle, Wnt signaling, and pathways in cancer; this analysis also showed that CCNE2, MYC, and CREB3L4 were the key involved genes." (PMID 28056099, 2017). "Motifs of SREBP, HIF, AP1, KLF, MYC, and FOX families are enriched in the H3K9me1/2-KDM ChIP-Seq data and were described to play a role in prostate cancer progression." (PMID 28416760, 2017). "The increased active nuclear beta-catenin through interaction with MYC/MAX transcription factor functions as a co-repressor of PrKD1 expression and thereby perpetuates the down regulation of PrKD1 in advanced prostate cancer." (PMID 29108267, 2017). "We used immunohistochemistry on each patient specimen to determine the expression of proteins that frequently undergo alteration in prostate cancer, including PTEN, TMPRSS2-ERG, MYC and Nkx3.1." (PMID 27351281, 2016). "A strong overlap of the identified eight FAIRE-seq peaks was found with known players in prostate cancer including AR, FOXA1, ERG, bromodomains BRD2 and BRD3 and, interestingly, MYC." (PMID 26412853, 2015). "We have also shown that SIRT3 suppresses prostate cancer growth both in vitro and in vivo by inhibiting the activation of PI3K/Akt, thereby leading to the destruction of oncoprotein c-MYC." (PMID 26317998, 2015). "Of the tested cell lines, MYCLo-4 was upregulated by MYC knockdown in HCT116 (CRC), RKO (CRC), HT29 (colorectal adenocarcinoma), A549 (Lung carcinoma) and PC3 (prostate cancer)." (PMID 26003165, 2015). "It is crucial to point out that SIRT3 suppresses prostate cancer progression through the inhibition of PI3K/Akt pathway and eventually down-regulation and destruction of oncoprotein c-MYC." (PMID 26317998, 2015). "Of the several transcription factors identified, a few namely E2F1, MYC, YY1, CHD1 and SMARCA4 which have been shown to express in prostate cancer tissues are of particular interest." (PMID 25938433, 2015). "Considering that activating mutations in the RAS/RAF/MEK/ERK signaling cascade are rare in prostate cancer, sustained stimulation of the MAPK pathway by ERα is a potential mechanism to increase MYC expression in a subset of prostate cancers." (PMID 25436982, 2015). "First, FOXP3 represses expression of the HER2, Skp2, SATB1 and MYC oncogenes, and induces expression of the tumor suppressor genes p21 and LATS2 in breast and prostate cancer cells." (PMID 24406338, 2014). "For both promoters and enhancers we also identified a subset of disruptive variants that target response elements for factors of special interest to prostate cancer, namely AR, FOXA1, NKX3-1, TCF7L2, MYC, GATA1 and GATA3." (PMID 24497837, 2014).